WASF2 (WASP family member 2)
Diseases named in the same sentence as WASF2 in open-access papers (continued):
Sharing a sentence is not in itself a finding about the gene and the disease.
type 1 diabetes (1 paper, 2007). "(III) Markers related to diseases other than cancer include WASF2, LCP2 and FYB (Wiscott-Aldrich syndrome, all up) and TAP2 (up, polymorphisms in this gene are implicated in type 1 diabetes." (PMID 19455236, 2007).
Wiskott-Aldrich syndrome (1 paper, 2024). Wiskott-Aldrich syndrome (WAS) is a primary immunodeficiency disease characterized by microthrombocytopenia, eczema, infections and an increased risk for autoimmune manifestations and malignancies. "WASF2 is named for its association with Wiskott-Aldrich syndrome, a rare genetic disorder which greatly increases the risk of various cancers (28–30, and31)." (PMID 38184653, 2024).
cancer (44 papers, 2007 to 2025). A tumor composed of atypical neoplastic, often pleomorphic cells that invade other tissues. "The TMSB4X, CNN3, TWF1, CORO1C and WASF2 genes encode cytoskeletal proteins related to actin filament dynamic regulation, and they are involved in cancer metastasis." (PMID 28159933, 2017). "The silence of circ_WASF2 inhibited cancer proliferation and increased cell death by increasing ferroptosis accompanied by up-regulation of lipid peroxidation, ROS, and Fe2+." (PMID 38704809, 2024). "The silence of circ_WASF2 inhibited cancer cell proliferation and increased cell death by increasing ferroptosis accompanied by up-regulation of lipid peroxidation, reactive oxygen species (ROS), and Fe2+." (PMID 38704809, 2024). "CRGs are a key link between cuproptosis and OC prognosis, a study showed that CRG WASP family member 2 (WASF2) promotes cancer cell proliferation and platinum resistance, and its high expression is associated with poor prognosis in OC patients." (PMID 39482784, 2024). "It confirms also that WASF2 is a main mediator of cancer progression via the histaminergic system with HRH2 in the CRC." (PMID 36902343, 2023). "In our study, we found that the expression of WASF2 was significantly associated with TMB in 9 cancer types and MSI in 9 cancer types." (PMID 35359421, 2022). "Due to the small number of normal tissue samples in TCGA database, the normal tissue data from the GTEx database and the tumor tissue data from TCGA database were combined to analyze the differences of WASF2 expression in 33 cancers." (PMID 35359421, 2022). "Next, the correlation between WASF2 level and infiltration of immune cells in pan-cancer was explored using Tumor Immune Estimation Resource (TIMER)." (PMID 35359421, 2022). "Wiskott-Aldrich syndrome protein family member 2 (WASF2) has been shown to play an important role in many types of cancer." (PMID 35359421, 2022). "We found that WASF2 expression correlated with cancer immunity, immune regulatory genes, TMB and MSI." (PMID 35359421, 2022). "We also explored the associations between WASF2 expression and immune infiltration levels, drug sensitivity, and tumor mutational burden (TMB) across 33 types of cancer." (PMID 35359421, 2022). "Our results indicated that WASF2 was highly expressed in a variety of cancers, and its expression level was closely related to many tumor progression, stage and prognosis." (PMID 35359421, 2022). "Nevertheless, most research studies on the roles of WASF2 in tumors were focused on individual cancer types and the sample sizes were often limited." (PMID 35359421, 2022). "In conclusion, our comprehensive pan-cancer analysis showed the characterization WASF2 within tissue and cell line." (PMID 35359421, 2022). "In conclusion, pan-cancer analysis of WASF2 was valuable for identifying differential expressions and the roles of WASF2 in many cancer types." (PMID 35359421, 2022). "WASF2 is a key molecule modulating the actin cytoskeleton and reconstruction; it influences the migration and invasion of cancer cells." (PMID 35477411, 2022). "In some epithelial‐originated tumors, activation of the Rac‐WASF2 pathway has been indicated to be correlated with the migration, invasion, and drug resistance of cancer cells." (PMID 35849030, 2022). "Our research further clarified that WASF2 had a wider range of tumor applicability, and confirmed that WASF2 expression was closely related to the biological processes of immune cells and immune-related molecules in most cancers." (PMID 35359421, 2022). "Patients with high WASF2 expression in HCC tissues (≥ 26% cancer cells) have a lower OS than those with low expression (≤ 25% cancer cells)." (PMID 35477411, 2022). "In this study, we conducted a comprehensive methodology for pan-cancer analysis and investigated the roles of the WASF2 in cancers." (PMID 35359421, 2022).
cancer (continued). "In the present study, we found that WASF2 was abnormally expressed across the diverse cancer and significantly correlated with overall survival (OS) and progression-free interval (PFI)." (PMID 35359421, 2022). "It has been demonstrated that microRNA-146a can target many genes, such as IRAK1, IRAK2, TRAF6, RIG-I, IRF-5, STAT-1, PTC1, Numb, and WASF2, to play a variety of roles in human diseases, including cancers and inflammatory immune diseases." (PMID 31798643, 2019). "In sum, these results suggested that WASF2 was abnormally expressed in different cancers." (PMID 35359421, 2022). "Moreover, WASF2 promoted invasiveness of cancer cells by binding to actin cytoskeletal protein alpha‐actinin 4 (ACTN4), and ACTN4 was associated with β‐catenin to regulate the adherence and movement of cells." (PMID 35849030, 2022). "Our current study showed that the WASF2 was highly expressed in 19 cancers and low in 5 cancers." (PMID 35359421, 2022). "In addition, WASF2 expression was associated with TMB, MSI, and antitumor drugs sensitivity across various cancer types." (PMID 35359421, 2022). "The relationship between WASF2 expression and the prognosis of patients in pan-cancer was analyzed." (PMID 35359421, 2022). "Therefore, it is important to further explore the pan-cancer relationship between WASF2 expression and TME." (PMID 35359421, 2022). "Our data showed that the expression of WASF2 in cancer cells could be regarded as a biological indicator to predict the sensitivity or resistance of cells to drugs, and provide effective support for subsequent basic research or clinical applications." (PMID 35359421, 2022). "First, the expression of WASF2 in 33 human cancers was analyzed by using TCGA and GTEx datasets." (PMID 35359421, 2022). "There has been so far no pan-cancer studies focusing on the association between WASF2 and various cancers." (PMID 35359421, 2022). "ATP1A1, KMT2E and WASF2 were known as the hallmarker of cancers and overexpression of these genes promote the survival of cancer cells, while RAD23A acts as a negative regulator of anti-virus response and might correlate directly with the HPV infection." (PMID 36420261, 2022). "Therefore, the dynamic reorganization of actin is a prerequisite for the migration of cancer cells; WASF2 is involved in the construction of the complex actin cytoskeleton." (PMID 35477411, 2022). "Additionally, higher WASF2 expression was observed in 12 different cancer types, particularly CHOL." (PMID 38968580, 2024). "Therefore, multi-omics pan-cancer analysis of the WASF2 can not only help to discover common phenotypic characteristics of tumors, but also carry out an in-depth interpretation about the causes of key molecular events and their own internal regulatory mechanisms." (PMID 35359421, 2022). "In addition, studies on WASF2 regulation in cancer cells are limited." (PMID 35477411, 2022). "In this study, we comprehensively analyzed the expression level of WASF2 and their relationship with prognosis in different types of malignancy from multiple public databases, such as TCGA, Genotype Tissue-Expression (GTEx), and Cancer Cell Line Encyclopedia (CCLE)." (PMID 35359421, 2022). "Other proteins are known inducers of epithelial to mesenchymal transition (EMT) (i.e. Laminins) or cancer cell spreading (i.e., CCN2, NPNT, WASF2, SERPINE, MAP4K4)." (PMID 40410902, 2025). "In the current study, we thoroughly examined the mRNA levels of NCKAP1, SLC7A11, WASF2, RAC1, SLC3A2, and RPN1 as well as the relationships between the mRNA levels of these six genes in pan-cancer." (PMID 38968580, 2024). "Correlation analysis also shows that the following histaminergic transcripts: GNA15, HRH2, MAOA, WASF2, and those related to inflammation: AEBP1, CXCL1, 2, 3, and 8, SPHK1, and TNFAIP6 play an important role in cancer tissue." (PMID 36902343, 2023).
cancer (continued). "Taking into consideration the cancer development process, the following histaminergic genes stood out: GNA15, HRH1-HRH4, MAOA, WASF2, along with inflammation-related genes: AEBP1, CXCL1, CXCL2, CXCL3, CXCL8, SPHK1, and TNFAIP6." (PMID 36902343, 2023). "Another example of such ‘promoter fusions’ is the recurrent WASF2–FGR fusion, which we found in three cancer types." (PMID 25204415, 2014). "Moreover, there is existing literature demonstrating the important roles of ABI3BP, WASF2, RUNX1T1, and TNFAIP8L2 in cancer processes through pan-cancer analysis." (PMID 37942289, 2023). "microRNA-1253 is a novel epigenetic regulator of WASF2 in human umbilical vein endothelial cells and human aortic endothelial cells; however, there are no studies on the epigenetic mechanisms that regulate WASF2 expression in cancer." (PMID 35477411, 2022). "This might indicate that the aberrant WASF2 expression wound affect the TMB and MSI of cancer, thus impacting the patient response to ICI." (PMID 35359421, 2022).
tumor (28 papers, 2008 to 2025). "In this study, we confirmed that WASF2 overexpression in HCC tumor tissues is associated with poor clinical outcomes in patients with HCC." (PMID 35477411, 2022). "To gain further insights into the regulatory effect of WASF2, we analyzed WASF2 expression in mouse and rat genomic datasets and assessed the tumor-suppressive effect of WASF2 knockdown in vivo." (PMID 35477411, 2022). "To validate the tumor suppressive effects of WASF2 knockdown in vivo, we subcutaneously injected siWASF2-transfected Huh-7 cells into BALB/c female nude mice." (PMID 35477411, 2022). "We performed IHC analysis using anti-WASF2, anti-Ki67, anti-Snail, and anti-cleaved caspase-3 in xenograft tumor sections from the Huh-7_siWASF2 and Huh-7_NC groups." (PMID 35477411, 2022). "The average tumor volume and WASF2 expression were significantly lower in the Huh-7_siWASF2 group than that in the Huh-7_NC group." (PMID 35477411, 2022). "This study elucidates that EMX1 functions as a tumor inhibitor in SCG by suppressing WASF2‐dependent activation of the Wnt/β‐catenin axis." (PMID 35849030, 2022). "The findings above suggested that restoration of WASF2 blocked the tumor‐suppressing role of EMX1 in SCG." (PMID 35849030, 2022). "cg24162579 CpG methylation in the WASF2 promoter was significantly downregulated according to HCC tumor stage (left); however, WASF2 expression was significantly upregulated (right)." (PMID 35477411, 2022). "We further conducted correlation analysis to explore the relationship between WASF2 expression and 33 tumor immune-related genes." (PMID 35359421, 2022). "The Cellminer database was used to explore the sensitivity of the WASF2 and common anti-tumor drugs, and we further calculated the correlation between the gene expression and the drug IC50." (PMID 35359421, 2022). "WASF2 mRNA and protein levels are higher in the HCC tissues than that in the paired surrounding non-tumor tissues (n = 31); they are significantly associated with aggressive tumor behavior such as multiple tumor number and vessel invasion." (PMID 35477411, 2022). "Clinically, cg24162579 methylation decreased and WASF2 expression increased according to HCC tumor differentiation grade." (PMID 35477411, 2022). "Furthermore, the expression levels of WASF2 in 30 tissue cell lines were analyzed using the data of tumor cell lines downloaded from the CCLE database." (PMID 35359421, 2022). "In addition, WASF2 knockdown using siWASF2 in a xenograft mouse model and a lung metastasis model exerted tumor suppressive effect." (PMID 35477411, 2022). "A positive correlation was observed between the expression of SNAI1 and WASF2 in the tumor group of the TCGA_LIHC dataset (Pearson’s correlation coefficient r = 0.26, P < 0.0001), but not in the non-tumor group (Pearson’s correlation coefficient r = 0.08, P = 0.55)." (PMID 35477411, 2022). "In addition, overexpression of WASF2 also reduced the size or tumor infiltration in mouse lung tissues after the tail vein injection of the SCG cells." (PMID 35849030, 2022). "Restoration of WASF2 blocked the tumor‐suppressing effect of EMX1." (PMID 35849030, 2022). "In addition, WASF2 hypomethylation was higher in the tumor group compared to that in the normal group, in 44 matched pairs of HCC patients from TCGA_LIHC data set." (PMID 35477411, 2022). "In summary, these results of this study might help elucidate the role of WASF2 in tumor occurrence and development." (PMID 35359421, 2022). "In addition, the precise regulatory mechanisms of WASF2 in the tumor microenvironment require further exploration in future studies." (PMID 35359421, 2022). "Meanwhile, this study provided a novel perspective on the roles of WASF2 in tumor immunotherapy." (PMID 35359421, 2022). "In addition, WASF2 has significant correlation with common tumor-related regulatory genes such as autophagy, DNA repair, ferroptosis, hypoxia, pyroptosis, and TGF-β signaling gene." (PMID 35359421, 2022).
tumor (continued). "Results showed that WASF2 was expressed in all 30 kinds of tumor cell lines." (PMID 35359421, 2022). "Notably, WASF2 was significantly overexpressed in HCC compared to that in non-tumor samples in three large cohort datasets (TCGA_LIHC, ICGC_LIRI, and GSE77314)." (PMID 35477411, 2022). "WASF2 is overexpressed in human HCC tissues compared to its levels in the surrounding non-tumor tissue and is positively correlated with poor overall survival (OS); however, the role of WASF2 in HCC cell phenotypes remains unclear." (PMID 35477411, 2022). "WASF2 inactivation resulted in tumor suppressive effects in the xenograft mouse model." (PMID 35477411, 2022). "Furthermore, the cg242579 CpG island in the WASF2 5′ promoter region was hypomethylated in HCC compared to that in the matched non-tumor samples." (PMID 35477411, 2022). "Studies have shown that WASF2 is closely related to the tumor immune microenvironment." (PMID 35359421, 2022). "miR-1 acts as a tumor suppressor, promoting the inhibition of tumor growth and acting with multiple target genes, such as CDK4, TMSB4X, WASF2, TWF1, CNN3, and CORO1C which are genes involved in cell cycle and metastasis." (PMID 38813102, 2024). "WASF1 and WASF2 belong to the WASF family and play an important role in cell invasion and migration, which are considered to be key steps in tumor metastasis." (PMID 37833936, 2023). "Therefore, WASF2 may be involved in the regulation of tumor immune microenvironment." (PMID 35359421, 2022). "Normal liver tissue had negative or medium NCKAP1, RAC1, RPN1, and WASF2 IHC staining, while tumor tissues had medium or strong staining." (PMID 38968580, 2024). "In addition to the decrease in CYFIP1 and WASF2 gene copy numbers in tumor samples, the copy number of other DGs increased to varying degrees, consistent with the decline in CYFIP1 and WASF2 gene expression in BC patients." (PMID 38035071, 2023). "WASF2 methylation and expression were significantly correlated with HCC tumor differentiation; therefore, we assessed their prognostic effects in patients with HCC according to WASF2 methylation and expression level, using the median beta value or median WASF2 expression as the threshold." (PMID 35477411, 2022). "We analyzed WASF2 promoter methylation levels in paired human HCC tissues using qMSP; 60 and 56% of the tumor tissues in the test (n = 20) and validation (n = 18) cohorts, respectively, were hypomethylated compared to non-tumor tissues." (PMID 35477411, 2022). "The overall rate of tumor growth was significantly lower in the WASF2-knockdown (Huh-7_siWASF2) group than that in the negative control (Huh-7_NC) group; in addition, the tumor size was lower." (PMID 35477411, 2022). "Subsequently, WASF2 was expressed positively in tumor tissue compared to that in non-tumor tissue." (PMID 35477411, 2022).
adenocarcinoma (2 papers, 2018 to 2023). A common cancer characterized by the presence of malignant glandular cells. "The presented results confirmed a greater expression of the WASF2 in the control tissue than in CRC adenocarcinoma, which may indicate a good prognosis for the patients." (PMID 36902343, 2023).
brain disorder (1 paper, 2025). A disease affecting the brain or part of the brain. "Two missense WASF2 variants, c.113G > A (p.Arg38Gln) and c.494T > C (p.Leu165Pro), were identified in patients with autism and NDDs103–105, but the functional alterations associated with brain disorders remain to be studied." (PMID 39774290, 2025).
WASF2 also shares sentences with these, for which no sentence is quoted: colorectal cancer (7 papers); cervical cancer (4); infection (4); glioblastoma (3); HIV-1 infection (3); invasive breast carcinoma (3); lung adenocarcinoma (3); liver cancer (2); anemia (1); bacterial infection (1); blood cancer (1); brain glioma (1); breast tumors (1); cardiomyopathy (1); colorectal (1); COVID-19 (1); cystadenocarcinoma (1); follicular thyroid carcinoma (1); genetic disorder (1); HCMV infection (1); immunodeficiencies (1); left ventricular noncompaction (1); leukemia (1); lymphopenia (1); meningioma (1); myopathy (1); non-small cell lung carcinoma (1); osteosarcoma (1); Parkinson's (1); renal cell carcinoma (1).
A further 5 diseases each share a sentence with WASF2 in 1 paper.